INS (insulin)
Diseases named in the same sentence as INS in open-access papers (continued):
Sharing a sentence is not in itself a finding about the gene and the disease.
malaria (continued). "However, high and medium concentrations of insulin seem to extend the lifespan of the vector similar to what was observed for malaria mosquitos." (PMID 35385472, 2022). "As expected, a stepwise linear regression model revealed that malaria-induced HOMAB, malaria-induced insulin, and baseline insulin levels were independent (R2 = 0.996; adjusted R2 = 0.994; P < 0.001) predictors of the observed HOMAIR level during malaria infection." (PMID 25587486, 2014). "Tukey's post hoc HSD test rather showed that, apart from the mean HOMAIR and serum insulin that increased significantly (P < 0.05) in diabetic respondents during malaria, the mean levels of all the other measured parameters were comparable (P > 0.05) before and during malaria." (PMID 25587486, 2014). "Indeed, quinine, which is commonly used for treatment of severe malaria in many parts of Africa, including Ghana, has been suggested to affect insulin secretion." (PMID 25614747, 2014). "Also, malaria-induced HOMAB correlated positively with baseline HOMAB (R = 0.66; P = 0.002) and malaria-induced insulin level (R = 0.686; P < 0.001)." (PMID 25587486, 2014). "Thus, although insulin level increased significantly due to malaria, probably to compensate for the increased resistance, the level was not high enough to overcome the observed resistance." (PMID 25587486, 2014). "During pregnancy, anthropometric measurements, blood film for malaria parasites and assays for lipids, glucose, insulin and TNF were obtained from 467 mothers and these analytes and insulin-like growth factor-I (IGF-I) were obtained from cord blood of 187 babies." (PMID 22429464, 2012). "Maternal malaria with cord blood insulin and IGF-I were significantly related to birth weight." (PMID 22429464, 2012). "Additionally, sex-specific pathways were identified, with AD male-specific pathways in the CA1 subfield including Estrogen signaling pathway (hsa04915), Toxoplasmosis (hsa05145), Malaria (hsa05144), Insulin secretion (hsa04911), and GABAergic synapse (hsa04727)." (PMID 38689734, 2024). "In addition, malaria parasites can also use insulin to their advantage." (PMID 39492784, 2024). "Therefore, malaria vectors feeding on malaria-infected persons may be exposed to even higher dosages of insulin, inducing various effects." (PMID 28700639, 2017). "Indeed, beyond the activity of Plasmodium GPIs as insulin mimetics, little is known of how malaria might alter the pathology of T2D and how treatment of T2D might impact malaria infection and, more specifically, transmission." (PMID 27102766, 2016). "In contrast to insulin, IGF-1 levels fall precipitously during a malaria episode, correlating well with the host’s increased parasitaemia." (PMID 28700639, 2017). "In a subsequent stepwise linear regression model, malaria-induced HOMAB and insulin were significant (P < 0.05; R2 = 0.954; adjusted R2 = 0.915) independent predictors of HOMAIR, jointly explaining over 91% of the observed variation." (PMID 25587486, 2014). "Similar analyses in the control group showed positive correlation of malaria-induced HOMAIR level with malaria-induced HOMAB (R = 0.479; P = 0.013), malaria-induced insulin (R = 0.978; P < 0.001), and baseline insulin level (R = 0.634; P = 0.011)." (PMID 25587486, 2014). "Malaria-induced HOMAIR correlated positively and moderately (R = 0.435; P = 0.001) but strongly (R = 0.901; P < 0.001) with malaria-induced HOMAB and insulin, respectively, in the diabetic group." (PMID 25587486, 2014). "In the presence of malaria, diabetics maintained significantly (P < 0.001) higher mean levels of BMI, FBG, and HbA1c but lower levels of serum insulin and HOMAB than controls." (PMID 25587486, 2014). "Levels of insulin, HOMA-B and HOMA-IR were highest for diabetics without malaria with high strengths of the associations." (PMID 40802820, 2025).
malaria (continued). "This positive correlational trend was observed between galectin-3 and insulin as well as HOMA-B in the non-diabetic respondents with malaria." (PMID 40802820, 2025). "Despite the reduction in virus titer seen in insulin-fed mosquitoes we do not recommend the feeding of insulin itself to mosquitoes given that this has been shown to enhance mosquito infection with malaria parasites." (PMID 39664493, 2024). "In malaria-infected diabetics, significant (P < 0.05) increase was only observed for insulin and HOMAIR but not the other measured parameters." (PMID 25587486, 2014). "A. stephensi can also respond to ingested human IGF1, which unlike insulin, declines in serum during malaria." (PMID 24968248, 2014). "The patient was simultaneously receiving quinine infusion, a drug well known to increase insulin secretion and reduce blood glucose, even in non-severe malaria." (PMID 18545693, 2008). "The negative correlation of age with HOMA-IR in our diabetic respondents without malaria corroborates a previous study that involved 169 non-diabetic Chinese respondents and could be ascribed to reduced insulin secretion and physical activity with age." (PMID 40802820, 2025).
liver dysfunction (36 papers, 2008 to 2026). "In one case, an asymptomatic patient had triglyceride levels exceeding 11,000 mg/dL associated with acute liver dysfunction, necessitating management with insulin infusion." (PMID 39958046, 2025). "MyD88 is one of the most important adaptor proteins in TLR signaling, and when MyD88 knockout mice are fed a high-fat chow diet, insulin and cholesterol levels increase and liver dysfunction appears, which are all associated with T2DM and NAFLD31." (PMID 37957232, 2023). "Liver dysfunction reduces insulin clearance and portosystemic shunting lowers hepatic insulin breakdown, raising systemic insulin levels." (PMID 40566506, 2025). "Unlike the BMI and WC, the VAI is proposed as an index capable of assessing liver dysfunction and insulin sensitivity." (PMID 38892518, 2024). "Our results from the first approach confirm these treatment and complication profiles, whereas the body fat-related and insulin-resistant subgroup from the second approach was dominated by liver dysfunction and cardiovascular events." (PMID 37402743, 2023). "Hepatopathy is one of the serious effects of DM Melatonin (MT) is a potent endogenous antioxidant that can control insulin output." (PMID 37655263, 2023). "In some RCT, high-dose insulin therapy or intensive insulin therapy reduced postoperative liver dysfunction, infections, and complications and improved the liver glycogen content in patients undergoing HPB surgery." (PMID 36310325, 2023). "Improvements in liver dysfunction by lifestyle intervention are considered to be a consequence of the restoration of insulin sensitivity." (PMID 27830836, 2016). "After careful consideration of different treatment options, and considering she had been free of hypoglycemic attacks for a few years and had liver dysfunction, we chose to cautiously initiate the patient on insulin therapy." (PMID 19829878, 2009). "This necessitates the use of disease models to explore how RSV influences insulin function in energy metabolism and whether it also influences liver dysfunction." (PMID 40806567, 2025). "Moreover, liver dysfunction can affect the metabolism and clearance of hormones, such as insulin, thyroid hormones, and sex hormones, necessitating specialized endocrine evaluation and management." (PMID 38731251, 2024). "It is also found that A. muciniphila supplementation may improve insulin sensitivity and blood lipid index, decrease body weight and fat mass and reverse liver dysfunction and inflammation biomarkers." (PMID 36079890, 2022). "Although such significant and adverse changes in blood lipids and lipoproteins can be ascribed to alterations in the serum level of hormones such as insulin and cortisol, the possibility of other reasons such as liver dysfunction and subsequent alteration in liver enzymes level cannot be ignored." (PMID 23497689, 2013). "Second, increased serum ferritin levels may reduce insulin sensitivity, which can increase the accumulation of free fatty acids through de novo synthesis of liver fat and decomposition of liver adipose tissue, directly leading to liver dysfunction." (PMID 37674440, 2023). "Circulating testosterone/DHT, insulin levels, prostate size and prostate volume were not statistically different between the 2 groups (Hyper vs. Normo), and these diets did not cause weight gain/loss or liver dysfunction (data not shown)." (PMID 22768301, 2012). "In addition, supplementation with Akkermansia muciniphila in overweight/obese patients could improve insulin sensitivity, reduce insulinemia, plasma TC, fat mass as well as hip circumference and decrease the levels of the relevant blood markers for liver dysfunction and inflammation." (PMID 37447278, 2023). "Serology showed no liver dysfunction, no statistical differences in triglyceride (TG) levels (trending higher in the HFHC cohort), & no statistical differences in insulin or IGF-1 levels (not shown)." (PMID 22279565, 2012).
renal dysfunction (36 papers, 2010 to 2025). "In addition, the rs9267551 C allele has been associated with lower levels of circulating ADMA, higher insulin sensitivity assessed by euglycemic-hyperinsulinemic clamp studies, and lower risk of renal dysfunction." (PMID 31409409, 2019). "First, advanced renal dysfunction is a potent independent risk factor for MI, as it induces systemic changes such as uremic toxicity, vascular calcification, and heightened inflammation, which may overshadow the contribution of insulin resistance to MI risk." (PMID 40948866, 2025). "Participants with renal dysfunction at baseline were older and showed significantly higher values of PP, fasting glucose, insulin, HOMA, UA and hs-CRP, and lower values of HDL-cholesterol and pre-bronchodilator FEV1." (PMID 34444971, 2021). "Similar alterations have been identified in diabetic patients with renal dysfunction, and the homocysteine levels were also positively correlated with insulin levels." (PMID 34457110, 2021). "The clinical effectiveness and better safety profile of newer mealtime insulin therapy may prompt a reconsideration of its use in patients with an advanced stage of renal dysfunction, leading to better adherence and improved quality of life." (PMID 31886089, 2019). "The justification for initiating the insulin therapy was: the persistence of fasting blood glucose levels > 200 mg/dL (41%), A1c > 9% (35%), the presence of catabolism (17%) and any contraindicating factor to the oral agents (e.g. renal dysfunction)." (PMID 30386438, 2018). "Indeed, incubating penguins only abandon their chick/egg to refeed when this state is associated with metabolic defects in glucose homeostasis/fatty acid utilization, insulin production and action, and possible renal dysfunctions." (PMID 27991520, 2016).
osteoarthritis (35 papers, 2011 to 2025). A noninflammatory degenerative joint disease occurring chiefly in older persons, characterized by degeneration of the articular cartilage, hypertrophy of bone at the margins and changes in the synovial membrane. "Additionally, the aberrant activation of the insulin signaling pathway is also associated with the occurrence of osteoarthritis and disturbances in bone metabolism." (PMID 40420260, 2025). "Results of the Mendelian randomization analysis of the effect of exogenous insulin on the incidence of osteoarthritis." (PMID 41398760, 2025). "Screening of IVs and F-test of instrumental variable strength for the use of exogenous insulin and osteoarthritis." (PMID 41398760, 2025). "Tests of horizontal pleiotropy of the Mendelian randomization analysis of the use of exogenous insulin on the onset of osteoarthritis." (PMID 41398760, 2025). "Multivariable Mendelian randomization analysis of the use of exogenous Insulin (ukb-b-7350) on the incidence of Osteoarthritis." (PMID 41398760, 2025). "It has been observed that insulin, either independently or in conjunction with inflammatory factors, can promote synovial inflammation during the advancement of osteoarthritis." (PMID 39200096, 2024). "Resistin is a new adipocytokine involved in the insulin signaling pathway, the pathogenesis of osteoarthritis 23,24, and promoting the proliferation and migration of vascular smooth muscle cells." (PMID 34659568, 2021). "In this study, we first discovered that insulin can promote synovial inflammation in the progression of osteoarthritis, either alone or in conjunction with inflammatory factors." (PMID 31981062, 2020). "Such a method has been used in several studies assessing potential associations between serum biomarker concentrations of leptin, adiponectin, and insulin in osteoarthritis (OA)." (PMID 27242922, 2016). "Restoration of FAHFAs—a lipid class with anti-inflammatory and insulin-sensitizing properties—may represent a metabolic biomarker indicative of therapeutic response in osteoarthritis." (PMID 41170378, 2025). "This study found that drinking water at 0°C reduces pepsin activity, leading to impaired function of the insulin signaling pathway, which may also be a potential metabolic mechanism by which the temperature of hot drinks affects osteoarthritis." (PMID 38035348, 2023). "As for osteoarthritis and DM, the top 5 most related genes were INS, TNF, IL-6, CRP, and IL-1B." (PMID 35719662, 2022). "Researchers also found that the disturbance of glucose metabolism induced by an insulin disorder may negatively affect articular cartilage, while insulin treatment ameliorated cartilage degeneration in an animal model of osteoarthritis." (PMID 25289023, 2014). "Additionally, GLP-1-based therapies, which enhance insulin secretion and improve glycemic control in DM, may exert protective effects in osteoarthritis by modulating inflammation, promoting cartilage repair mechanisms, and potentially slowing joint degeneration." (PMID 39200096, 2024). "In one study, patients with DISH and those with osteoarthritis had elevated levels of insulin and growth hormone, however, the level of IGF-1 was higher in patients with DISH than in those with osteoarthritis." (PMID 23049626, 2012). "Overall, the data from randomized placebo-controlled osteoarthritis trials have not shown any adverse effects on fasting blood glucose levels, glucose metabolism, or insulin sensitivity from oral GlcN, at any dose level." (PMID 21218504, 2011). "Using ex vivo synovial explants from RA patients and osteoarthritis (OA) non-inflammatory controls, the activity of glucose transporters GLUT1 (largely insulin-dependent) and GLUT4 (activated under the influence of insulin) was measured." (PMID 32899806, 2020).
pneumonia (34 papers, 2008 to 2026). An acute, acute and chronic, or chronic inflammation focally or diffusely affecting the lung parenchyma, caused by an infection in one or both of the lungs (by bacteria, viruses, fungi, or mycoplasma.). "Our study also revealed that older people, persons with comorbidities, using more oral antidiabetic drugs, insulin, and aspirin had a higher risk of pneumonia." (PMID 36876083, 2023). "In our study, we built up different patient groups according to a stable antidiabetic drug therapy of 4 years and we found an increased risk of pneumonia in type 2 diabetic patients treated with insulin." (PMID 34683125, 2021). "The combination of insulin and statins and the combination of insulin, metformin and statins were also related to increased risk of pneumonia in both sexes." (PMID 34683125, 2021). "In a sex-specific analysis, insulin monotherapy was related to an increased pneumonia risk in both males (2.02, CI: 1.35–3.03, p < 0.001) and females (OR: 2.17, CI: 1.40–3.37, p < 0.001)." (PMID 34683125, 2021). "In detail, insulin as monotherapy (OR: 2.07), but also in combination with statins (OR: 2.24) or with statins and metformin (OR: 2.27) was related to an increased risk of pneumonia." (PMID 34683125, 2021). "Regarding treatment, the use of insulin was a risk factor for pneumonia in our study." (PMID 34552886, 2021). "Pneumonia and GI sepsis can disrupt the normal function of endocrine organs involved in glucose metabolism, affecting insulin secretion and exacerbating dysglycemia." (PMID 39258039, 2024). "At that time, he was admitted to a general medical ward with preliminary impressions of pneumonia and diabetic ketoacidosis and received antibiotic therapy and insulin." (PMID 36034605, 2022). "Insulin mitigates pneumonia by inhibiting NEDD4L, thereby boosting the expression of the epithelial sodium channel via the phosphatidylinositol 3‐kinase–protein kinase B (PI3K–Akt) pathway." (PMID 35355403, 2022). "A possible mechanism behind an increase in pneumonia cases in insulin-treated patients is the immunomodulatory nature of insulin itself." (PMID 34683125, 2021). "In our study, the overall mortality, death from cancer, and death from pneumonia and respiratory conditions were significantly higher in the insulin users compared with the non-insulin users after adjustment for all potential confounders." (PMID 23308218, 2013). "Similarly, the RABBIT-2 Surgery trial demonstrated that basal-bolus insulin reduced perioperative complications, such as wound infections and pneumonia, compared to SSI." (PMID 39939862, 2025). "The use ratio of insulin was notably higher in the pneumonia group regardless of the administered oral agents." (PMID 34552886, 2021). "Specifically, patients treated with insulin monotherapy, but also in combination with statins, metformin or DPP-IV inhibitors, had an increased risk of diagnosis of pneumonia when compared to individuals without antidiabetic drug therapy." (PMID 34683125, 2021).
Huntington disease (33 papers, 2009 to 2026). Huntington disease (HD) is a rare neurodegenerative disorder of the central nervous system characterized by unwanted choreatic movements, behavioral and psychiatric disturbances and dementia. "Huntington’s disease (HD) is associated with aggregates of mutant huntingtin (mHtt), which interfere with insulin signaling in neurons due to the accumulation of dysfunctional mitochondria." (PMID 37456463, 2023).